SIX3 (SIX homeobox 3)
Diseases named in the same sentence as SIX3 in open-access papers (continued):
Sharing a sentence is not in itself a finding about the gene and the disease.
extraskeletal myxoid chondrosarcoma (1 paper, 2011). A rare malignant soft tissue neoplasm of uncertain differentiation, characterized by the presence of chondroblast-like cells in a myxoid stroma and a multinodular growth pattern. "SIX3 regulates the transcriptional activity of the orphan nuclear receptor NOR-1 (NR4A3), which regulates the survival of cells, and acts as a part of the EWS/NOR-1 fusion protein, implicating the oncogenesis of human extraskeletal myxoid chondrosarcoma (EMC)." (PMID 21962230, 2011).
Hyperglycemia (1 paper, 2016). An increased concentration of glucose in the blood. "In this model, the key genes regulating eye development, Pax6, Six3 and Otx2, were downregulated by hyperglycemia." (PMID 26744353, 2016). "Results showed that the expression of Pax6, Six3 and Otx2 were significantly inhibited by hyperglycemia, but other genes, such as Mitf, Rx1 and Chx10, were not affected significantly (data not shown)." (PMID 26744353, 2016). "Moreover, the Pax6 plasmid restored the expression of Six3 and Otx2 to levels that were nearly normal, suggesting that hyperglycemia-induced suppression of Pax6 is the upstream event." (PMID 26744353, 2016).
leukemia (1 paper, 2025). A malignant (clonal) hematologic disorder, involving hematopoietic stem cells and characterized by the presence of primitive or atypical myeloid or lymphoid cells in the bone marrow and the blood. "Similarly, SIX3 and SOBP regulate transcription and development, influencing leukemia cell differentiation." (PMID 40506993, 2025).
lung squamous cell carcinoma (1 paper, 2016). "Based on our result and previous publication, we proposed that SIX3 might promote the initiation of NSCLC, but inhibit tumor progression once tumor formed, especially in the early stage of lung squamous cell carcinoma." (PMID 27821176, 2016). "Subgroup analysis of lung squamous cell carcinoma (SQC) showed no significance in SIX2 and SIX3." (PMID 27821176, 2016).
microcephaly (1 paper, 2019). A congenital or acquired developmental disorder in which the circumference of the head is smaller than normal for the person's age and sex. "Interestingly, Six3 regulates Shh, one robust candidate for microcephaly that has been positively selected in the human lineage, but it also interacts with several genes relevant for our language-ready brain (Benítez-Burraco and Boeckx, 2015)." (PMID 30971880, 2019).
pituitary disease (1 paper, 2023). "The interaction of Pou1f1 and Six3 in mice supports the possibility of digenic pituitary disease in children." (PMID 35951005, 2023). "While the role of POU1F1 has been well defined in pituitary disease, less is known about the role of SIX3." (PMID 35951005, 2023). "Studies in mice and cell lines have demonstrated that SIX3 is important for development of hypothalamic neurons, fertility and growth, but more studies are necessary to understand the mechanism of SIX3 action and role in pituitary disease." (PMID 35951005, 2023).
retinal degeneration (1 paper, 2025). Degeneration of the retina. "TUNEL staining showed significant apoptosis of Chmfl/y; Six3-Cre mouse associated with retinal degeneration." (PMID 41429839, 2025).
Stroke (1 paper, 2021). Sudden impairment of blood flow to a part of the brain due to occlusion or rupture of an artery to the brain. "However, it is unclear whether SIX3 functions in neuronal repair after stroke; further research should, therefore, be conducted to confirm this." (PMID 35096003, 2021).
Visual impairment (1 paper, 2023). "The unaffected father and one sibling with visual impairment carried the SIX3 p.P74R/+ variant, but they did not have CPHD." (PMID 35951005, 2023).
tumor (16 papers, 2010 to 2026). "By univariate analysis, we found that SIX3 mRNA expression was significantly associated with gender, tumor size, or ECOG PS." (PMID 23977152, 2013). "We further examine how SIX3 can act either as a tumour suppressor or as a marker of poor prognosis in different cancer types." (PMID 41892811, 2026). "In this case, similarly to bulk endpoint tumor expression patterns, Nanog, Six3, Dcx, but interestingly, also increased Calca expression, was reversed." (PMID 41413044, 2025). "In cancer studies, SIX3, appeared to function as a tumor suppressor, where overexpression in cancer cells was associated with decreased proliferation." (PMID 34490256, 2021). "Wnt signaling has been shown to play a significant role in cancer stem cell maintenance and metastasis and repression of Wnt by Six3 supports its role as a tumor suppressor." (PMID 34490256, 2021). "qRT-PCR and IHC showed that SIX3 was expressed at a much lower level in tumor than in normal brain tissues and that the expression was independent of World Health Organization histological grades." (PMID 32051553, 2020). "As a tumor suppressor, SIX homeobox 3 (SIX3) can inhibit the expression of some metastasis and proliferation-related genes." (PMID 31097003, 2019). "Paradoxically, we found that the high expression of SIX3 was detected in tumor tissues and it was related to the advanced stage in NSCLC or ADC but not in SQC." (PMID 27821176, 2016). "Furthermore, some other TRIMs have been reported to be engaged in tumor cell proliferation; for example, SIX3 is ubiquitinated and degraded by TRIM27, and TRIM27-SIX3 signaling induces cell proliferation and metastasis in NSCLC." (PMID 36249749, 2022). "The transcription factor Six3 is a member of the SIX family and is generally regarded as a tumor suppressor." (PMID 34545072, 2021). "In stark contrast to other SIX transcription factors, increased levels of SIX3 appear to play a tumor suppressive role rather than an oncogenic one." (PMID 34490256, 2021). "We constructed a novel seven-gene signature (B3GALT5-AS1, DNER, CSN1S1, KIF5A, SIX3, NOTUM, and CPS1) and a combined prognostic model integrating a seven-gene signature with patient age and tumor size to quantify the likelihood of distant metastasis in lymph node-negative TNBC." (PMID 34604089, 2021). "Considering SIX3 is the only SIX family member that does not interact with EYA, which is an oncogene, it is reasonable to comprehend the tumor suppression features of SIX3." (PMID 27821176, 2016).
cancer (12 papers, 2012 to 2026). A tumor composed of atypical neoplastic, often pleomorphic cells that invade other tissues. "We also demonstrate that epigenetic events affecting SIX3 lead to its silencing, loss of function and consequent cancer cell proliferation and metastasis." (PMID 23977152, 2013). "Recent studies suggest SIX3 and other SIX family genes regulate the proliferation and differentiation pathways implicated in cancer." (PMID 40506993, 2025). "In this study, we investigated the germline mutation alterations of ADAM6, SIX3, GNAS, NDUFV1, H19, DEFA4, and ZIM2 genes in 82 pediatric cancer patients treated with cisplatin." (PMID 41009448, 2025). "The transcriptional regulator Sox2 has been shown to be directly regulated in developmental and cancer contexts by Six1, Six2, Six3, and Six6 to further promote stem/progenitor cell phenotypes." (PMID 34490256, 2021). "The ectopic expression of SIX3 has also been observed in several human cancers, although it may have a dual effect on cancers." (PMID 28595628, 2017). "SIX3 expression and clinical characteristics in cancer patients." (PMID 23977152, 2013). "Clinically, lung tissue samples of cancer patients showed increased TRIM27 expression and decreased SIX3 expression." (PMID 33264103, 2020).
infection (7 papers, 2014 to 2026). The state of being infected such as from the introduction of a foreign agent such as serum, vaccine, antigenic substance or organism. "In comparison to the mock control, a similar reduction in the expression of RAX and SIX3 was detected in ectodermal cells after infection with both RV strains." (PMID 31405163, 2019). "Pax6 or Six3 expression vectors were introduced into mES or hES cells by transfection or lentiviral infection and the differentiating ES cells analyzed for lens marker expression." (PMID 25517354, 2014). "Similarly, when Six3-GFP was expressed in G4 mES cells at 21 days post-infection, Six3 GFP expressing cells were often found close to γA-crystallin positive cells, but the two markers only rarely co-localized to the same cell." (PMID 25517354, 2014). "In line with this, the expression of the virulence effector genes SIX1 and SIX3 at 6 DPI was significantly reduced in ∆kmt6a, further suggesting that this mutant is blocked at an early stage of root infection before reaching the xylem, where SIX genes are fully activated." (PMID 41495884, 2026). "In addition, expression of the protein-coding genes CXCL10, IFIT1, NCOA7, IFIT2, SIX3, and RPSA was increased during infection." (PMID 40510596, 2025). "Here, we investigated SIX3, 5, and 9 gene expression in the Fusarium strains isolated from onions and SIX2 and 9 gene expression in the Fusarium strains isolated from Welsh onions during infection." (PMID 39057818, 2024).
nervous system diseases (2 papers, 2019 to 2021). "Among these genes, Ch25h, Trpa1, Cdkn1a, Ly6g6e, Six3, and Opalin are potentially associated with neurological diseases; Lcn2, Serpina3f, Lao1, Trim29, bcl3, and Gkn3 are associated with inflammatory response." (PMID 30804943, 2019). "The mRNAs of Rgs9, Gpr88, Drd2, Sh3rf2, Tac1, Serpina 9, Rxrg, Drd1, Rasgrp2, Six3, Gpr6, Pdyn, Gng7, and Pde1b were all upregulated (p < 0.05); all of these have been reported to be more or less related to nervous system diseases." (PMID 33819195, 2021).
adenocarcinoma (1 paper, 2013). A common cancer characterized by the presence of malignant glandular cells. "SIX3 expression was also significantly associated with improved OS in adenocarcinoma patients with BAC features." (PMID 23977152, 2013). "Our data demonstrate the prognostic significance of SIX3 expression in adenocarcinoma and BAC." (PMID 23977152, 2013). "Moreover, we demonstrate clinical relevance of SIX3 expression levels in patients with adenocarcinomas and BAC." (PMID 23977152, 2013). "Therefore, it is possible that genomic and genetic differences between BAC and adenocarcinomas without BAC features account for the different prognostic values of SIX3." (PMID 23977152, 2013).
SIX3 also shares sentences with these, for which no sentence is quoted: epilepsy (2 papers); acute T-cell leukemia (1); breast tumor (1); chondrosarcoma (1); developmental delay (1); hepatocellular carcinoma (1); hypertensive (1); Kallman syndrome (1); lentivirus infection (1); Lissencephaly (1); microphthalmia (1); mucoepidermoid carcinoma (1); neurodevelopmental disorder (1); ocular hypertension (1); pancreatic adenocarcinoma (1); periodontitis (1); prostate adenocarcinoma (1); Schinzel-Giedion syndrome (1); Usher syndrome (1); velocardiofacial syndrome (1); viral infection (1).